HK2 (hexokinase 2)
Diseases named in the same sentence as HK2 in open-access papers (continued):
Sharing a sentence is not in itself a finding about the gene and the disease.
tumor (continued). "LND, a derivative of indole-3-carboxylic acid, was initially reported as a contraceptive and later repurposed as an anti-tumor drug due to its anti-Warburg effect and inhibition of HK2 activity." (PMID 39990654, 2025). "Given the essential role of HK2 in glycolysis and resultant protein lactylation, we generated a KPC cell line with knockdown (KD) of Hk2 and used it for an orthotopic mouse tumor model." (PMID 39883522, 2025). "HIF-1α, stabilized under hypoxic conditions, further enhances HK2 transcription, linking tumor hypoxia in the TME to increased HK2 expression." (PMID 40520908, 2025). "This decline in HK2 activity impairs glycolysis, a metabolic pathway essential for tumor energy metabolism, which in turn results in elevated PD-L1 levels." (PMID 40382627, 2025). "For example, the miR-654-3p was found to be inhibited by circular RNA pyridoxal kinase (circPDXK), which was highly expressed in tumor tissues and cells of OC patients, leading to upregulation of HK2 expression." (PMID 40045411, 2025). "The E3 ligases HUWE1 and tumor necrosis factor receptor-associated factor 6 can ubiquitinate metabolic enzymes including hexokinase 2 and affect tumor growth by regulating glycolysis." (PMID 39823500, 2025). "Beyond CAF activation, TGF‐β critically modulates fibroblast metabolism via TGF‐β1/Smad signaling, which under hypoxic conditions synergistically induces MCT4/glycolytic enzyme overexpression (LDHA, PKM2, and HK2) and tumor EMT to potentiate metastasis." (PMID 40772466, 2025). "Hk2 KD in the tumor cells significantly decreased Pan-Kla and p-STAT3 levels in TAMs but not in other immunocytes, indicating that TAMs are the primary immune cells affected by tumor-derived lactate." (PMID 39883522, 2025). "Depletion of CD8+ T cells from the mice partially offset the tumor-inhibiting effect (60% vs 27%) by Hk2 KD in comparison with the control mice." (PMID 39883522, 2025). "HK2 is overexpressed in many cancers and is a key driver of glucose metabolic reprogramming, which supports tumor proliferation, survival, and immune evasion." (PMID 40181966, 2025). "Compared with control treatment, NLRP12 overexpression significantly increased tumor burden parameters (size/volume/weight), whereas HK2 knockdown significantly decreased these tumorigenic metrics." (PMID 40796546, 2025). "MCL1 impacts metabolism via modulating the expression of hexokinase 2 (HK2) in an mTORC1-dependent manner, which ultimately contributes to the tumor-promoting effects of MCL1." (PMID 41326406, 2025). "As the initial rate-limiting enzyme in the glycolysis process, HK2 is believed to directly participate in the metabolic reprogramming of tumor cells." (PMID 39991762, 2025). "Among the known HK isoforms, HK2 is predominant in tumor tissues and can promote tumor progression through its metabolic and non-metabolic functions." (PMID 40164592, 2025). "On one hand, it promotes WTAP expression and stimulates aerobic glycolysis in tumor cells via the miRNA-200-hexokinase 2 (HK2) axis." (PMID 41446042, 2025). "Studies have shown that upregulation of hexokinase 2 (HK2) correlates with enhanced glycolysis and tumorigenesis, while HK2 inactivation reduces glycolysis and suppresses tumor growth and metastasis." (PMID 40382627, 2025). "Some compounds have also shown potential in inhibiting HK2-mediated enhancement of glycolysis in tumor cells." (PMID 39991762, 2025). "And HK2 not only participates in glycolysis, but also activates the NF-κB pathway, promotes PD-L1 expression, and leads to tumor immune escape." (PMID 41281744, 2025). "A previous study on post-translational modifications has reported that HK2 has many lysine sites that allow ubiquitination, and the ubiquitination of HK2 has been reported to occur in some tumor cells." (PMID 40796546, 2025).
tumor (continued). "After administering OA, the protein expression level of Beclin-1 was prominently up-regulated, and the protein expression levels of p62, GLUT1, and HK2 were markedly down-regulated in the tumor tissue (P<0.0001)." (PMID 40969279, 2025). "By decreasing mTOR activity, a negative regulator of autophagy, HK2 can enhance autophagic processes, contributing to increased tumor cell resistance to TAM therapy." (PMID 40303296, 2025). "HK2 is known to be upregulated in various cancers, promoting tumor progression; however, high activity of hexokinases has also been detected in endosalpinx (mucous membrane lining the fallopian tubes), where glucose is a major metabolic fuel." (PMID 40563592, 2025). "Tumor endothelial cells (ECs), under hypoxic conditions, exhibit enhanced glycolytic flux, evidenced by the upregulation of glycolytic enzymes such as hexokinase 2 (HK2), PKM2, and LDHA." (PMID 41281744, 2025). "Our findings reveal that FBZ suppresses tumor growth by inducing pyroptosis and inhibiting glycolysis via HK2 downregulation." (PMID 40756987, 2025). "In multiple tumour contexts, low SHBG states are associated with increased c-Myc and Bcl-2 expression and activity, upregulation of glycolytic effectors GLUT1, LDH and HK2, promoting mitochondrial resistance to apoptosis." (PMID 41586225, 2025). "Analysis of tumor-infiltrated lymphocytes revealed that KD of Hk2 or inhibiting CCL2 signaling in KPC tumors reduced monocyte/macrophage infiltration but enhanced T cell infiltration and function." (PMID 39883522, 2025). "HK2, as the foremost rate-limiting enzyme in glycolysis, exhibits high expression in numerous tumor cells and plays a pivotal role in the enhanced glycolysis of tumors." (PMID 39991762, 2025). "Previous studies have indicated that CHD1 supports tumor growth by modulating metabolic genes such as HK2 and LDHA, with its inhibition suppressing proliferation and inducing apoptosis, particularly in PTEN-deficient models." (PMID 41249788, 2025). "PVT1 also promotes glycolysis and tumor growth via the miR-497/hexokinase 2 (HK2) axis, further linking it to metabolic reprogramming in OS." (PMID 41301848, 2025). "Overall, targeting HK2 significantly increases tumor radiosensitivity and shows promise for improving therapeutic outcomes." (PMID 41441035, 2025). "By directly binding to the m6A-modified 3′-UTR of HK2 mRNA, IMP2 stabilizes HK2 and elevates its protein levels, thereby accelerating aerobic glycolysis and tumor progression." (PMID 40141058, 2025). "Immunohistochemical analysis of tumor tissues revealed that Liensinine treatment led to a marked reduction in the expression levels of HK2, PDK1, and HIF-1α, while increasing the expression of IDH3B, UQCRC1, and phosphorylated AMPK (P-AMPK)." (PMID 40665352, 2025). "In particular, the localization and attachment of HK2 to the outer mitochondrial membrane allow tumor cells to cope with many stressful conditions by intersecting both metabolic and anti-apoptotic pathways." (PMID 39770959, 2024). "As the rate‐limiting enzyme in glycolysis, HK2 plays a crucial role in initiating the glycolytic pathway, and is highly expressed in several types of tumours." (PMID 39661501, 2024). "Consistent with previous studies, our results confirmed the significant upregulation of HK2 expression in malignant tumours, emphasizing its potential as a therapeutic target." (PMID 39713255, 2024). "It has been reported that HK2 expression in immune cells is positively correlated with higher immune cell infiltration in the tumor microenvironment (TME)." (PMID 39260692, 2024). "Our qRT-PCR result showed that HK2 mRNA expression was upregulated in GC tumor tissues and positively correlated WNT5A expression." (PMID 39054546, 2024). "The importance of HK2 during HCC development has been previously reported since liver specific HK2 deficiency decreases HCC cell proliferation and tumor development in response to DEN treatment." (PMID 38424041, 2024).
tumor (continued). "Inhibiting HK2 can inhibit tumor growth, regulate the Warburg effect, and improve tumor drug resistance." (PMID 38686047, 2024). "Metformin simultaneously suppresses glycolysis and OXPHOS by inhibiting HK2 and impairing mitochondrial function, effectively depriving the tumor of vital energy sources." (PMID 39479443, 2024). "In the acidic tumor microenvironment, the nanocomplex rapidly disintegrates, liberating 2-DG to inhibit glycolysis via HK2, while metformin targets mitochondrial OXPHOS." (PMID 39479443, 2024). "Another study determined that increased HK2 promotes tumor growth and resistance to apoptosis of cancer cells." (PMID 38479191, 2024). "This phase 0 first-in-human study evaluated the biodistribution, normal-tissue dosimetry, and tumor targeting of 111In-radiolabeled h11B6 ([111In]-DOTA-h11B6) to evaluate hK2 as a target in patients with mCRPC." (PMID 38782459, 2024). "Wu found that dioscin promotes the interaction of c-Myc and FBW7 to promote c-myc ubiquitination, which in turn inhibits the expression of HK2 to reduce tumor glycolysis and induce cell apoptosis." (PMID 39330497, 2024). "In various in vitro and in vivo tumor models, multiple compounds effectively target HK2, inducing its dissociation from mitochondria and subsequently initiating apoptosis in tumor cells." (PMID 38720279, 2024). "The glycolysis dependence of ECs in tumor vessels is even greater than that of ECs in the normal activated state, accompanied by enhanced expression of Glut1 and HK2." (PMID 38933335, 2024). "Prior studies have highlighted the critical role of HK2 in promoting tumour growth and progression by facilitating increased glycolytic activity." (PMID 39713255, 2024). "The results of Western blot and IHC demonstrated that the expressions of p‐STAT3 and HK2 were promoted in tumor from nude mice with NSD3‐knockout PC9 cells." (PMID 39119928, 2024). "TGF-β1 serves as an upstream positive regulator of urothelial carcinoma-associated 1 (UCA1), which in turn is an upstream positive regulator of hexokinase-2 (HK2), and tumor-promoting lncRNA TGF-β1 tends to be up-regulated in tissues." (PMID 39346921, 2024). "Numerous genetic and biochemical changes contributed to the molecular basis of the high rate of glycolysis in tumour cells, which included the elevated HK2 expression." (PMID 38590647, 2024). "At the same time, emerging literatures have underlined that HK2 expression is boosted in OSCC tissues and cells and intensifies the aggressive phenotypes of tumor cells." (PMID 38671310, 2024). "Dioscin inhibits glycolysis by inducing Skp2 ubiquitination and inhibiting HK2 in tumor tissues, which is dependent on the Skp2-Akt-HK2 axis." (PMID 39330497, 2024). "Glabridin induces tumor cell apoptosis by upregulating the pro-apoptotic gene Bax and downregulating the anti-apoptotic gene Bcl-2 while inhibiting glycolysis by reducing HK2 and LDHA expression." (PMID 39723390, 2024). "In OS tumor tissues and cells, we also observed the high HK2 and LDHA expression at the protein levels." (PMID 38218855, 2024). "Research has demonstrated that HK2 is involved in aberrant metabolism in tumour cells and serves as a key regulatory factor in tumour development." (PMID 39661501, 2024). "This includes increased expression of GLUT family members that import more glucose into tumor cells, as well as rate-limiting enzymes like hexokinase 2 (HK2) and lactate dehydrogenase A (LDHA)." (PMID 39273409, 2024). "For example, HK2 initiates glycolysis by converting glucose to glucose-6-phosphate, accelerating tumor growth." (PMID 39906672, 2024). "HK2 is a main driver of tumor pericyte glycolysis, which (via the ROCK2-MLC2 pathway) increases pericyte contractility, resulting in impaired blood flow in tumors." (PMID 38798921, 2024). "HE, IHC staining and WB showed the expression of MAT1A, CCND1, proliferation marker Ki67 and glycolytic marker (ALDOC, HK2) in tumor tissues, emphasizing the regulation of MAT1A and CCND1 on NSCLC cells." (PMID 39438468, 2024).
tumor (continued). "Reduced HK2 expression or using HK2 inhibitors underpins increased inhibition of aerobic glycolysis in animal models, restraining tumor proliferation, migration, and metastasis." (PMID 38994113, 2024). "The role of HK2 in inhibiting tumor cell growth has been confirmed in breast cancer, oral cancer, and cervical cancer." (PMID 39877360, 2024). "The significant increase in HK2 expression in tumours is believed to result from metabolic reprogramming that meets the demands of accelerated tumour growth." (PMID 38590647, 2024). "It has been shown that hexokinase 2 (HK2)-driven glycolysis is elevated in tumor pericytes, which upregulates their ROCK2-MLC2-mediated contractility, leading to impaired vascular support function." (PMID 38778409, 2024). "In mouse tis-sues, Hk2 expression was significantly increased in tumours from HF/C mice, while Pfkl expression was significantly decreased in tumours from both C/C and HF/C mice." (PMID 39203941, 2024). "The heightened glycolytic rate of tumor cells can be attributed to their elevated expression of HK2." (PMID 38720279, 2024). "Various tumor types upregulate glycolytic enzymes including hexokinase 2 (HK2), providing these cells with a competitive advantage for metabolism within the TME." (PMID 39227970, 2024). "Western blot indicated that WNT5A and HK2 were upregulated by CAFs in mice tumor, while decreased when WNT5A was silenced in CAFs." (PMID 39054546, 2024). "The involvement of AKT-induced HK2 expression and activity in tumor growth was reported in different types of cancer, including in PCa." (PMID 39339236, 2024). "Research has shown that HK2 is upregulated in various tumours and is involved in the occurrence and development of tumours (cervical cancer, liver cancer, prostate cancer)." (PMID 38288377, 2024). "Aberrant upregulation of HK2 has been observed in various cancer types, promoting tumour growth, progression, metastasis, and drug resistance." (PMID 39713255, 2024). "Our findings highlight the interplay between metabolic enzymes and tumor immunity, suggesting that HK2 serves as an effective molecular biomarker for PD-L1 antibody therapy." (PMID 37377974, 2023). "Phosphorylation of HK2 at Thr473 by PIM2 enhances HK2 stability and activity and promotes glycolysis, tumor growth, and drug resistance to paclitaxel." (PMID 37143582, 2023). "A landmark study on an adult tumor model of mice demonstrated the therapeutic effects of systemic deletion of HK2." (PMID 37109475, 2023). "In oesophageal cancer, UCA1 can promote tumour glucose metabolism via the UCA1/miR-203/HK2 axis, contributing to cancer cell proliferation and metastasis." (PMID 36639695, 2023). "Tumor cells largely express the HK2 subtype, which has a high affinity for glucose to ensure it enters the glycolysis process efficiently, whereas normal cells largely express the HK1 subtype." (PMID 37190313, 2023). "Secreted protein acidic and rich in cysteine (SPARC) can regulate glucose metabolism in tumor cells, and such a process is related to HK2." (PMID 38076208, 2023). "Membrane-associated RING-CH 8 promotes ubiquitination-mediated proteasomal degradation to reduce HK2 protein levels, thereby regulating and repressing glycolysis to promote tumor suppressors in colorectal cancer." (PMID 37415097, 2023). "It is reported that overexpression of HK2 increases tumor cell glycolysis, and a high level of HK2 is relevant to poor prognosis in DLBCL patients." (PMID 37367892, 2023). "In non-small cell lung cancer, Piperlongumine can reduce the expression of HK2, inhibit the glycolysis of cancer cells, and accelerate cancer cell apoptosis to achieve anti-tumor effects." (PMID 37582735, 2023). "MYC is a ‘master regulator’ of glycolysis and tumour proliferation, which can transcriptionally upregulate several key genes involved in aerobic glycolysis like HK2 and PKM2." (PMID 36752127, 2023).
tumor (continued). "HK2 is a key glycolytic enzyme and a key regulator of switching the energy metabolism of tumour cells from glycolysis back to mitochondrial respiration." (PMID 37740039, 2023). "A high expression of HK2 in tumors promotes tumor growth by maintaining higher glycolysis rates in cancer cells." (PMID 37569773, 2023). "On the other hand, it has been described that HK2-driven glycolysis in pericytes activates their contractile properties, leading to tumour blood vessel abnormalities, while the administration of an HK2 inhibitor induced tumour vasculature remodelling." (PMID 36765947, 2023). "Based on this, some scientific researchers have developed precise combinations of drugs with HK-2 inhibitors, which have produced more effective killing effects on tumour cells." (PMID 37108242, 2023). "HK2 predominantly exists in insulin-sensitive tissues and tumor cells, and its functions include metabolic rewiring of glycolysis, regulation of autophagy, and shielding from cell death stimulation." (PMID 38090580, 2023). "We demonstrated that GULT1 and HK2 protein levels were positively correlated with PLEKHG2 expression in tumor tissues both in vivo and in vitro." (PMID 38021149, 2023). "HK2 was found to drive glycolysis in tumor-derived pericytes and regulate the blood vessel supporting ability of pericytes by inducing Rho-associated coiled-coil containing protein kinase 2 -myosin light chain 2 (ROCK2-MLC-2) driven contractility." (PMID 36984785, 2023). "HIF1α is upregulated due to hypoxia brought about by the tumor microenvironment, which results in the upregulation of HK2, making HK2 the most highly expressed HK in multiple tumors." (PMID 37109475, 2023). "We quantified the expression of glycolytic markers, HIF-1α, GLUT1 and HK2 as a percentage of total neutrophils determined by CD15 + CK- cells in the tumor sections and adjacent matched normal tissues." (PMID 36614196, 2023). "Overexpression of HK-2 frequently occurs in various tumors, resulting in enhanced glucose metabolism, resistance to cell apoptosis, and tumor-invading capacity." (PMID 38114977, 2023). "HK2 inhibition in tumor-derived pericytes supported the blood vessel formation ability and improved the efficacy of doxorubicin against tumor formation." (PMID 36984785, 2023). "An enzyme in glucose metabolism, HK2, is necessary for the growth and maintenance of many tumors due to tumor cells being active in metabolism." (PMID 37509689, 2023). "Circ_0008928 highly expressed in serum exosomes and cells of cisplatin-resistant NSCLC patients can sponge miR-488 and upregulate HK2 to promote glycolysis and tumor progression." (PMID 37365670, 2023). "have reported that HK2 had the potential to enhance tumor proliferation, growth, invasion, and metastasis via regulation of lactate metabolism in PC." (PMID 37234801, 2023). "In the meantime, a significant decrease of epidermal growth factor receptor activity and hexokinase-2 expression were seen in kaempferol-treated tumor tissue." (PMID 37239974, 2023). "We provide evidence that the fructolytic proteins Glut5, KHK, and HK2 are all expressed in two endothelial cell lines, and that fructose can be absorbed and metabolized by these cells and contribute to tumor angiogenesis." (PMID 37507736, 2023). "For example, we recently reported that inhibiting glycolysis in PDAC tumor-conditioned macrophages in vitro, using a competitive HK2 inhibitor (2-deoxyglucose), reversed their pro-metastatic phenotype." (PMID 36614196, 2023). "Specifically, MMP9, MMP13, MMP11, and CEMIP were positively associated with the tumor immune microenvironment, while SLPI, SLC2A1, SERPINB5, HK2, CEACAM6, and CEACAM5 were negatively associated with the tumor immune microenvironment." (PMID 37234801, 2023). "Taken together, our findings and previous reports suggest that HK2 acts as a tumor metabolic driver in the DLBCL phenotype." (PMID 37854321, 2023).